SMAD3 (SMAD family member 3)
Diseases named in the same sentence as SMAD3 in open-access papers (continued):
Sharing a sentence is not in itself a finding about the gene and the disease.
tumor (continued). "In three Smad3 knockout mouse models from different laboratories, only one has been reported to develop spontaneous colon carcinomas, but later studies suggest the tumor development is related to a helicobacter infection." (PMID 22204491, 2011). "First, in the TRAMP model, we previously found that tumor development triggers enhanced TGF-β-dependent Smad2 and Smad3 phosphorylation in the tumor-draining lymph nodes compared to other tissues examined including the prostate." (PMID 22248703, 2011). "To determine the consequence of the IL-6 and TGF-β increment, we investigated the cytokine-coupled transcriptional factor signals of STAT3 and Smad3 which were identified as important factors responsible for malign tumor progress." (PMID 20520770, 2010). "This is consistent with the notion that a high threshold of Smad3 is necessary to induce TGF-β -mediated anti-tumor responses." (PMID 19190755, 2009). "CITED2, on the other hand, interacts with Smad2 and Smad3 to induce expression of the matrix metalloproteinase 9 gene in TGF-β-mediated tumor cell invasion." (PMID 19883516, 2009). "We have previously demonstrated that, when transiently expressed in hepatic cells, HCV core proteins isolated from tumor or cirrhotic nodules bind Smad3 differently and that this interaction inhibits Smad3-dependent transcriptional activity." (PMID 19190755, 2009). "Smad3 inactivation also completely blocked TGF-β-induced EMT, further supporting the notion that Smad3 plays a crucial role in both tumor suppressor and pro-metastatic effects of TGF-β in carcinogenesis." (PMID 19190755, 2009). "In the majority of tumours (nuclear or cytoplasmatic) expression of Smad3 (91%; 279 of 309 tumours) and Smad4 (100% or all 305 tumours) was found." (PMID 17692120, 2007). "Nuclear expression in the stroma was detected in 46% (143 of 310) of tumours for Smad3 and 97% (301 of 309) for Smad4." (PMID 17692120, 2007). "Diurnal expressions of Smad3 and Smad7 mRNA were observed in tumor‐infiltrated CD8+ T cells." (PMID 41257391, 2026). "TGFβ1 was positive in the stroma, and SMAD3 was positive in tumor cells." (PMID 41187938, 2025). "Therefore, we posit that the SMAD3-mediated metabolic reprogramming in SSCs, in contrast to tumor cells, likely represents a more controlled regulatory process that mitigates cellular damage." (PMID 40721814, 2025). "Here, western blot analysis showed that the expression of p-GSK3B and p-SMAD3 in 22RV1 cells and PC-3 tumor cells was significantly upregulated compared to that in RWPE-2 cells, suggesting that the EPHB1-GSK3B-SMAD3 signaling pathway was activated during PRAD development." (PMID 40548257, 2025). "Moreover, treatment with SIS3, a specific SMAD3 inhibitor, significantly improved CD107a expression in CD56dim tumor-infiltrating NK cells (TINKs)—a subset where we observed increased SMAD2–3 phosphorylation compared to their liver-resident counterparts." (PMID 41268557, 2025). "Moreover, we found that HLA class I expression on tumor cells was significantly downregulated in tumor regions with a higher proportion of p-Smad3-positive tumor cells." (PMID 40801643, 2025). "Thus, boosting Smad3 expression directly drives the maturation of tumor MO-MDSC into MΦ and DC in vitro." (PMID 41360769, 2025). "Actually, Smad3 expression is inherently higher in monocytic lineage compared to granulocytic lineage whether in a tumor or normal state, indicating a preferential role for Smad3 in monocytic development." (PMID 41360769, 2025). "Overexpressing SMAD3 in SKBR3 cells reduced the sensitivity of tumor cells to T-DM1 treatment." (PMID 40925917, 2025). "Indeed, Smad3 levels in MDSC decreased at early-stage tumors (the diameter of tumor tissue was between 5 and 8 mm on the 8th day of CT26 model construction) and further as tumors progressed." (PMID 41360769, 2025). "We next examined whether enhancing Smad3 expression could rescue MO-MDSC maturation in tumor-bearing Lyz2-Smad3 mice." (PMID 41360769, 2025).
tumor (continued). "Indeed, the decay rate of Smad3 mRNA was significant increased from 0.97 hours to 3.04 hours in tumor MO-MDSC after Mettl3 knockdown." (PMID 41360769, 2025). "Moreover, phosphorylation of Smad3 at linker residues (T179, S204, S208), a modification known to attenuate tumor‐suppressive functions of Smad3, was also significantly diminished." (PMID 40083231, 2025). "In addition, PTTG1 can inhibit the TGF-β1/SMAD3 signaling pathway, thereby suppressing apoptosis and promoting tumor cell growth." (PMID 41312363, 2025). "We discovered that tumor-derived exosome carrying 3′tiRNA-AlaCGC target fibroblasts, inducing a senescence-associated secretory phenotype (SASP) and activating the TGF-β/Smad3 pathway to increase Galectin-9 secretion; both SASP and Galectin-9 are known to induce CD8+T cell exhaustion." (PMID 40855047, 2025). "Importantly, we investigated the differential expression of BCL6, NFIB and SMAD3 in the tumor tissue samples and cell lines, with the findings indicating that these three genes are most highly expressed in CRPC and C42B‐ABi cells." (PMID 40470696, 2025). "However, BAZ1A is associated with cellular senescence by regulating Mothers Against Decapentaplegic homolog 3 (SMAD3) and p21 in tumor cells." (PMID 41278204, 2025). "TGFβ and its downstream effector SMAD3 play a dual role in tumor development." (PMID 41187938, 2025). "However, the simultaneous knockdown of both Smad2 and Smad3 has a stronger effect on promoting in vivo tumor growth than the knockdown of Smad2 alone, suggesting that Smad3 plays a supporting role in the tumor suppressor function of Smad2." (PMID 38569937, 2024). "The levels of p-SMAD3 in tumor tissues were assessed through IHC and WB analysis." (PMID 39353900, 2024). "However, the intensity of ERG expression is typically weaker than that observed in the endothelium of surrounding vessels (or that observed in EWSR1::SMAD3-rearranged tumor) and comparison with these structures is diagnostically useful." (PMID 39264472, 2024). "Univariate Cox regression analysis results showed that SMAD3 expression (p = 0.004, HR = 1.727, 95% CI 1.185–2.517), tumor stage (p = 0.014, HR = 1.270, 95% CI 1.049–1.539), and age (p = 0.010, HR = 1.025, 95% CI 1.006–1.045) considerably affected the overall survival of NSCLC patients." (PMID 38493128, 2024). "Genes for both Smad2 and Smad3 can be accepted as tumor suppressor genes." (PMID 38256080, 2024). "Similarly, high levels of expression of Smad3 are required for its tumor suppressor function, whereas low expression of Smad3 is sufficient for its tumor-promoting function in mouse mammary epithelial cells." (PMID 38569937, 2024). "The results suggested the synergistic inhibitory effect of SMAD3 knockdown on tumor growth in vivo." (PMID 38514720, 2024). "Smad3 signaling plays a key role in maintaining this pro-tumor N2 state." (PMID 39759220, 2024). "To determine whether the ZFP36L1, SDC4 and p-SMAD3 levels are correlated in OS, we collected 70 patient tumor tissue sections." (PMID 37935976, 2024). "Importantly, treatment of MC38 tumor-derived TILs with the SMAD3 inhibitor (E)-SIS3 significantly enhanced the expression of effector cytokines in CD44+CD8+ T cells, confirming the critical role of SMAD3 activation in suppressing memory CD8+ T cell function." (PMID 38971819, 2024). "In terms of treatment, targeted methylation of SMAD3 can inhibit tumor cell metastasis." (PMID 38514720, 2024). "In turn, in the xenograft tumor mouse model, SMAD3 knockdown inhibited tumor formation." (PMID 39337574, 2024). "Together, these findings demonstrated that SMAD3 knockdown inhibited tumor immune escape in vivo." (PMID 38514720, 2024). "In parallel, comparing with mice treated with Smad3 wild-type NK cells, the proportion of GM-CSF producing NK in the tumor microenvironment was largely promoted in those treated with Smad3 knockout NK cells, but reversed in mice treated with GM-CSF-silenced Smad3 knockout NK." (PMID 38878186, 2024).
tumor (continued). "Moreover, CSC percentages and tumor‐initiating capabilities were markedly reduced in cells with SOX2 or SMAD3 stable knockdown as measured by limited dilution and tumorigenic assays." (PMID 39206755, 2024). "The inhibition of BRD4 and SMAD3 through BETi or genomic editing can be valuable therapeutic strategies to exploit the anti-tumor potential of NK cells in adoptive NK/CAR-NK cell therapies or, alternatively, to rescue/enhance autologous NK activity in TME of NSCLC patients." (PMID 38519469, 2024). "Furthermore, lncRNA H19 has been found associated with the regulation of TGF-β/SMAD3 in HCC, impacting tumor growth." (PMID 38279330, 2024). "SMAD3 may act as a tumor suppressor by blocking c-Myc transcription and stimulating p15 production to activate G1 arrest." (PMID 38756663, 2024). "We demonstrated that SMAD3 knockdown inhibited tumor immune escape in vivo." (PMID 38514720, 2024). "Additionally, the role of neutrophils and macrophages in the tumor microenvironment is increasingly being recognized as a potential therapeutic avenue, with Smad3 emerging as a key target." (PMID 39759220, 2024). "Consistent with our previous findings, tumor metabolic activity in mice receiving Smad3 knockout NK cell therapy was 80% lower than mice receiving Smad3 wild-type NK cell therapy as determined by bioluminescence imaging, suggesting Smad3 significantly suppresses the anti-cancer activity of NK cells." (PMID 38878186, 2024). "Likewise, reducing NK-derived GM-CSF with si-RNA also nullified the protective effects of Smad3 knockout NK cell therapy on the recruitment of M1 macrophages, which was aligned with the changes of GM-CSF levels in the tumor tissue." (PMID 38878186, 2024). "Similarly, the number of tumor-infiltrated iNOS+ M1 was markedly increased in mice receiving Smad3 knockout NK cell therapy as compared with those receiving Smad3 wild-type NK cell therapy." (PMID 38878186, 2024). "In breast cancer, bFGF enhances the recruitment of bone mesenchymal stem cells (BMSCs) and their transdifferentiation into CAFs, potentially via the Erk1/2 and Smad3 pathways, leading to increased tumor cell proliferation and collagen production in the tumor microenvironment." (PMID 39796710, 2024). "Thus, to further understand tumor invasiveness specifically induced by JICD1/SMAD3-TWIST1 axis, we compared tumors derived from control, JICD1-overexpressing, and JICD1-overexpressing with TWIST1 knockdown U87MG cells." (PMID 38092725, 2023). "In addition, an IHC assay with the transplanted tumours indicated high expression of p-SMAD3, MMP2, MMP9 and MMP14 in the control group." (PMID 37689715, 2023). "pSMAD3L and pSMAD3C, the isomers of SMAD3 phosphorylation, are reversible and antagonistic, and the balance may shift from carcinogenesis to tumour suppression." (PMID 37685308, 2023). "Interestingly, in tumors high tumor abundance, SMAD3 and KLF4 high, and PPARG low expression, were significantly associated with poor prognosis, albeit small sample size." (PMID 38129585, 2023). "SMAD2 and SMAD3 are the main downstream effectors of TGF-β, and despite their 84% protein sequence homology and similar activation patterns, there is growing evidence that SMAD2 and SMAD3 play different and opposing functions including cell invasion, tumour growth, and metastasis." (PMID 37685308, 2023). "Under low active TGF-β1 conditions as in early tumour stages, the enhanced migration of high SMAD3 fibroblasts may be a major contributor to the larger TAF recruitment observed in ADC compared to SCC." (PMID 36572730, 2023). "SMAD3 was significantly overexpressed in tumor tissues compared with normal tissues in TCGA." (PMID 37790613, 2023).
tumor (continued). "TGF‐β treatment reversed the decreases in the proliferation, invasion and migration of tumor cells induced by SCRN1 knockdown as well as the decrease in p-SMad3 expression in OSCC cell lines, suggesting that SCRN1 acts promotes OSCC by modulating the TGF‐β/Smad3 pathway." (PMID 37691034, 2023). "In addition, deletion or knock-down of Smad3 in mouse or human neutrophils augmented their cytotoxic response to tumor cells in vitro." (PMID 37002229, 2023). "Interestingly, a recent study revealed that inhibition of SMAD3 linker domain phosphorylation results in reduced tumor growth and metastasis." (PMID 38092725, 2023). "Further studies are warranted to compare optimal Tgfbr1 inhibition versus optimal Smad3 inhibition in the LLC tumor model, and whether a Tgfbr1 inhibitor provides any added benefit when given to Smad3-KO mice." (PMID 37002229, 2023). "We next examined whether SMAD3 regulates N1/N2 polarization and tumor killing in human neutrophils in vitro and in vivo using the human NSCLC cell line, A549." (PMID 37002229, 2023). "Similarly, miR-450b-5p, suppressed in RMS by TGF-β1 through a pathway mediated by Smad3 and Smad4, exerted anti-tumour effects in tumour implants and cells by arresting RMS growth and upregulating MyoD expression." (PMID 36765536, 2023). "In addition, mechanisms by which Smad3 regulates the polarization of BMDN stimulated with tumor cell cultured media was investigated at the genome level via ChIP-seq and unbiased bioinformatic analysis." (PMID 37002229, 2023). "In addition, 61/112 genes were upregulated in knockout mice for Fshr and for three other tumor suppressor genes (Pten, Cdh1 and Smad3) known to regulate follicular homeostasis in the mammalian ovary." (PMID 38203684, 2023). "In addition, the function of TGF-β1/Smad3 is highly dependent on the environment, and its tumor suppressive effect is reported in a cell-type-specific manner." (PMID 37205317, 2023). "In vitro data indicate that activin A plays its tumor‐promoting roles in a SMAD3‐dependent manner." (PMID 37083240, 2023). "Furthermore, we found that the suppression of circEif3i, a homologous circRNA of circEIF3I in mouse, also inhibited tumour metastasis by impairing SMAD3 phosphorylation." (PMID 37689715, 2023). "Finally, we carried out IHC for phosphorylated SMAD family member 3 (pSMAD3-ser425) as a surrogate for TGFβ signalling activation status in the tumours in a subset of the initial L1-IHC cohort." (PMID 36707636, 2023). "Hence, the study demonstrates that miR-193b is an oncogene that promotes cell growth by directly targeting SMAD3 and restricting the tumour-suppressive effects of SMAD3 through p21 down-regulation in GBM." (PMID 37891744, 2023). "In addition, the research also found that there are abundant SMAD3 exosomes in the peripheral blood of patients with HCC, and its level is related to the stage of the disease and the expression of Smad3 in the primary tumor." (PMID 35812745, 2022). "EZH2-mediated tumor metastasis depends on SMAD3 methylation." (PMID 35085106, 2022). "Deletion of SMAD3 K53/K333 methylation can dramatically inhibit tumor metastasis." (PMID 35085106, 2022). "As an example, transforming growth factor-β1 (TGF-β1) increases the expression of the programmed cell death-1 (PD-1) receptor by enhancing antigen-driven PD-1 gene transcription through Smad3 transcriptional activation in T cells in vitro and in tumor-infiltrating lymphocytes in vivo." (PMID 35432324, 2022). "Moreover, a significant reduction in p-SMAD3 levels was seen in MCU knockdown tumours by western blot analysis." (PMID 35490194, 2022). "Additionally, SMAD3 up-regulated LINC09177 transcription by simultaneously binding the promoter and SE, which was induced by the infiltration of M2-like tumor-associated macrophages (TAM2), subsequently activating the TGF-β/SMAD3 pathway." (PMID 35982471, 2022).
tumor (continued). "However, in this study, we have demonstrated that docetaxel repressed tumor progression through Smad3-mediated tumor glycolysis in vivo and in vitro through HIF-1α, thereby inhibiting cell proliferation." (PMID 36536346, 2022). "SMAD3 suppresses tumor growth by preventing cell division and encouraging apoptosis." (PMID 36704357, 2022). "In addition, JPHYD significantly inhibited the expression of miR21-5p and the protein levels of Smad3, Vimentin, Snail, and N-cadherin, while E-cadherin and Smad7 proteins increased in tumor tissues treated with JPHYD." (PMID 35518787, 2022). "Importantly, VilCreER;Apcfl/+;KrasG12D/+;Alk5CA tumours exhibited high expression of the Alk5CA transgene and prominent p-SMAD3 staining, in contrast to APC-deficient tumours lacking Kras mutation." (PMID 36477656, 2022). "The TGF-β/SMAD3 pathway plays an indispensable role in tumor development." (PMID 35413833, 2022). "Thus, the impact of Smad3 on Tak1 splicing turns a tumor-suppressing signal into a tumor-promoting one." (PMID 36644295, 2022). "Encouragingly, the MMT‐driven CAF formation (α‐SMA) as well as LLC‐tumor growth in the Smad3‐WT BMDM‐received mice was significantly reduced by the macrophage‐specific silencing of Smad3 (Smad3‐KO BMDM), suggesting Smad3 as a potential therapeutic target for eliminating MMT‐driven CAF formation." (PMID 34791825, 2022). "Here, we discovered how TGF-β1/Smad3 signaling promotes tumor innervation by TAM via a direct mechanism, which may represent a previously unidentified therapeutic target for handling cancer pain in the future." (PMID 36206343, 2022). "Docetaxel/Smad3 axis suppressed tumor glycolysis and tumor growth in vivo." (PMID 36536346, 2022). "Furthermore, over-expression of GDF-10 brings about the up-regulation of p-SMAD3, consequently promoting the activation of stromal fibroblasts and the proliferation and migration of tumor cells." (PMID 36714584, 2022). "On the other hand, SMAD3 expression and activation at the tumor cellular level may serve as a marker for tumor proliferation, metastasis, and patient prognosis." (PMID 35002714, 2021). "Additionally, we observed an increase in the number of ducts in these tissues compared to the tumor tissues from the control mice, and the cells positive for phosphorylated SMAD3 were mainly clustered around these ducts." (PMID 34439202, 2021). "During oncogenic progression, this tumor suppressant phosphorylation of SMAD3 can be inhibited." (PMID 34771508, 2021). "SMAD3 exhibits both constitutive (host-driven) and inducible (tumor-driven) expression in cancer." (PMID 35002714, 2021). "Overall, these findings indicate that miR-32-5p serves as a tumor suppressor by targeting SMAD3." (PMID 33758603, 2021). "Huang and colleagues, reported that high preoperative p-SMAD3 tumor expression could be a potential predictor of poor response to nCRT in LARC patients." (PMID 35002714, 2021). "Finally, to determine the clinical significance of the role played by Smad3 in OS tumor progression, we investigated Smad3 gene expression using data extracted from the GSE21257 database." (PMID 34765560, 2021). "Third, considering the effect of SMAD3 on the tumor aggressiveness phenotype, regardless the impact on chemoradiotherapy, a non-treated control group would have been helpful to clarify the contribution of SMAD3 on tumor response to treatment." (PMID 35002714, 2021). "SMAD3 was upregulated in tumor tissues compared with the adjacent normal lung tissues." (PMID 33758603, 2021). "We focused on the top 3 tumor‐promoting genes: SMAD3, BIRC3, and SCL9A5." (PMID 33724679, 2021). "This study demonstrates that tumor SMAD3 protein expression and germline genotype could predict response to fluoropyrimidine-based nCRT." (PMID 35002714, 2021). "Thus, SMAD3 aids the tumor suppression effect of TGF-β by serving as a mediator of TGF-β-induced apoptosis." (PMID 34579396, 2021).